STARD9 (StAR related lipid transfer domain containing 9)
Description:
Microtubule-dependent motor protein required for spindle pole assembly during mitosis. Required to stabilize the pericentriolar material (PCM).
Synonyms: KIAA1300; KIF16A
Tractability: PROTAC: ubiquitination databases record sites on it.
Gene: Protein-coding gene on chromosome 15 (42,575,606 to 42,720,998, forward strand). Ensembl gene ENSG00000159433.
Subcellular location: Cytoplasm, cytoskeleton, microtubule organizing center, centrosome, centriole; Nucleus
Gene Ontology:
Molecular function: microtubule binding; microtubule motor activity; ATP binding; lipid binding
Biological process: spindle assembly; microtubule-based movement
Cellular component: centriole; cytoplasm; nucleus
Genetic constraint (gnomAD): Loss-of-function variants: 317 observed, 382.71 expected, observed/expected ratio (o/e) 0.83, 90% interval 0.75 to 0.91. The upper end of that interval is the gene's LOEUF score, 0.91, which puts it in group 3 of 6, group 1 being the genes least tolerant of losing a copy. Missense variants: 5,658 observed, 5,744.7 expected, observed/expected ratio (o/e) 0.98, 90% interval 0.96 to 1.01. Synonymous variants: 2,151 observed, 2,194.2 expected, observed/expected ratio (o/e) 0.98, 90% interval 0.94 to 1.02.
Homologues: Orthologues: chimpanzee STARD9 (99% identical), macaque STARD9 (91% identical).
Diseases named in the same sentence as STARD9 in open-access papers:
STARD9 is named in the same sentence as 13 diseases in open-access papers, as found by Europe PMC text mining. Sharing a sentence is not in itself a finding about the gene and the disease. The quoted sentences say what the papers report.
absence seizures (1 paper, 2025). "Four genes-HESX1, NCKAP1, SON, STARD9-had not been previously associated with absence seizures." (PMID 41137852, 2025).
Ataxia (1 paper, 2023). Ataxia refers to impaired coordination of voluntary muscle movement. "Also similar to mouse models of NPC disease, StARD9 KO mice develop tremors, ataxia, loss of grip strength and abnormal walking gait in that order." (PMID 36861884, 2023). "StARD9 KO mice developed comparable neurodegeneration phenotypes to those of NPC mutant mice, with loss of Purkinje cells and the development of tremors, ataxia, loss of grip strength and abnormal walking gait." (PMID 36861884, 2023).
dwarfism (1 paper, 2025). "For example, a homozygous nonsense mutation within the START domain of STARD9 was reported in a patient with microcephaly and dwarfism." (PMID 41373726, 2025).
Intellectual disability (1 paper, 2019). "The STARD9 gene is necessary for spindle assembly during cell division in human development, and a mutation in the gene might cause a syndrome with intellectual disability." (PMID 30930738, 2019).
cancer (3 papers, 2017 to 2021). A tumor composed of atypical neoplastic, often pleomorphic cells that invade other tissues. "Stard9 is involved with the regulation of spindle pole assembly and has been linked to mitotic arrest and cancer." (PMID 34794440, 2021). "Although the role of STARD9 in cancer development is still unknown, the inhibition of STARD9 function may be an appropriate approach to inhibit the division of cancer cells." (PMID 34572920, 2021).
tumor (1 paper, 2013). "Of note, we identified newly emerged 8 non-synonymous somatic mutations of the genes (ACAP2, CARD10, KIAA0556, PAAQR7, PPP1R39, SAFB2, STARD9, and ZFYVE9) in the imatinib-resistant tumor tissue." (PMID 23922791, 2013).
STARD9 also shares sentences with these, for which no sentence is quoted: asthenospermia (1 paper); deafness (1); microcephaly (1); multinodular goiter (1); neutropenia (1); pituitary tumor (1); Tremor (1).